TPM3 (tropomyosin 3)
Description:
Binds to actin filaments in muscle and non-muscle cells. Plays a central role, in association with the troponin complex, in the calcium dependent regulation of vertebrate striated muscle contraction. Smooth muscle contraction is regulated by interaction with caldesmon. In non-muscle cells is implicated in stabilizing cytoskeleton actin filaments.
Synonyms: TRK; CAPM1; CFTD; CMYO4A; CMYO4B; CMYP4A; CMYP4B; HEL-189; HEL-S-82p; NEM1; OK/SW-cl.5; TM-5; TM3; TM30; TM30nm; TM5; TPM3nu; TPMsk3; hscp30
Tractability: PROTAC: ubiquitination databases record sites on it; its protein half-life has been measured.
Gene: Protein-coding gene on chromosome 1 (154,155,308 to 154,194,648, reverse strand). Ensembl gene ENSG00000143549.
Subcellular location: Cytoplasm, cytoskeleton
Subcellular location (Human Protein Atlas): Actin filaments; Cytosol
Pathways (Reactome):
Muscle contraction: Smooth Muscle Contraction; Striated Muscle Contraction
Disease: Signaling by ALK fusions and activated point mutants
Signal Transduction: RHOV GTPase cycle
Gene Ontology:
Molecular function: protein binding; actin filament binding
Biological process: actin filament organization; muscle contraction
Cellular component: extracellular exosome; mitochondrion; stress fiber; actin filament; cytoskeleton; cytosol; muscle thin filament tropomyosin
Genetic constraint (gnomAD): Loss-of-function variants: 13 observed, 40.44 expected, observed/expected ratio (o/e) 0.32, 90% interval 0.21 to 0.51. The upper end of that interval is the gene's LOEUF score, 0.51, which puts it in group 2 of 6, group 1 being the genes least tolerant of losing a copy. Missense variants: 166 observed, 327.18 expected, observed/expected ratio (o/e) 0.51, 90% interval 0.45 to 0.58. Synonymous variants: 97 observed, 116.67 expected, observed/expected ratio (o/e) 0.83, 90% interval 0.7 to 0.98.
Gene-disease validity (ClinGen):
ClinGen rates the evidence that TPM3 causes each of these diseases.
TPM3-related myopathy (autosomal dominant; autosomal recessive): Definitive. TPM3-related myopathy is a disorder of the musculoskeletal system that covers a wide spectrum of phenotypes and is caused by pathogenic variants in the skeletal muscle γ-Tropomyosin gene.
Homologues: Orthologues: dog TPM3 (100% identical), macaque TPM3 (100% identical), mouse Tpm3 (99% identical), rat Tpm3 (99% identical), pig TPM3 (93% identical), guinea pig TPM3 (92% identical), zebrafish tpm3 (87% identical), chimpanzee TPM3 (73% identical), tropical clawed frog tpm3 (65% identical), Drosophila melanogaster Tm1 (56% identical), Caenorhabditis elegans lev-11 (55% identical), Drosophila melanogaster Tm2 (48% identical). Paralogues in human: TPM1 (91% identical), TPM2 (86% identical), TPM4 (63% identical).
Diseases named in the same sentence as TPM3 in open-access papers:
TPM3 is named in the same sentence as 123 diseases in open-access papers, as found by Europe PMC text mining. Sharing a sentence is not in itself a finding about the gene and the disease. The quoted sentences say what the papers report.
nemaline myopathy (20 papers, 2010 to 2025). Nemaline myopathy (NM) encompasses a large spectrum of myopathies characterized by hypotonia, weakness and depressed or absent deep tendon reflexes, with pathologic evidence of nemaline bodies (rods) on muscle biopsy. "Among the participants with congenital myopathy, one was diagnosed with nemaline myopathy, one with inflammatory myopathy, and one with myopathy associated with a tropomyosin 3 gene mutation." (PMID 40638490, 2025). "The distribution of type I and type II muscle fibers were significantly abnormal in patients with nemaline myopathy caused by NEB gene, however, it was basically normal in patients with nemaline myopathy caused by TPM3 gene and ACTA1 gene." (PMID 37525074, 2024). "The patient had poor head control and failure to thrive, but no hypomimia, and his upper limbs were clearly weaker than his lower limbs, features which in combination with the histopathology suggested TPM3-caused nemaline myopathy." (PMID 37393515, 2023). "Numerous missense mutations in TPM3, the gene encoding the muscle tropomyosin (Tpm) isoform Tpm3.12, have been associated with nemaline myopathy, cap disease, and congenital fiber-type disproportion." (PMID 38003645, 2023). "Pathogenic variants in the TPM3 gene, encoding slow skeletal muscle α-tropomyosin account for less than 5% of nemaline myopathy cases." (PMID 37393515, 2023). "Biallelic pathogenic variants and heterozygous pathogenic variants in TPM3 cause autosomal recessive or autosomal dominant nemaline myopathy, 1, respectively which accounts for ~ 2–3% of cases of nemaline myopathy." (PMID 33827624, 2021). "Point mutations in TPM3 encoding slow skeletal Tpm3.12 are involved in two known skeletal muscle myopathies: nemaline myopathy (NM) and congenital fiber type disproportion (CFTD)." (PMID 31270709, 2020). "In a mouse model of TPM3 nemaline myopathy, the onset of muscle weakness, caused at least partially by hypotrophy of type 1 fibers, appeared to be delayed by compensatory hypertrophy of type 2 fibers, as in human patients." (PMID 31228046, 2019). "TPM3 (tropomyosin 3) is associated with nemaline myopathy, which presents as typically type 1 fiber hypotrophy, and mutations in the TPM3 gene can induce congenital fiber-type disproportion, which is characterized by generalized muscle weakness." (PMID 30486769, 2018). "For example, mutations in CHRNB2 are associated with nocturnal frontal lobe epilepsy and TPM3 mutations are associated with nemaline myopathy." (PMID 21821125, 2012). "Dominant mutations in ACTA1 and TPM3 are most frequently associated with nemaline myopathy characterized by early onset and respiratory insufficiency, while recessive forms of nemaline myopathy are most frequently associated with mutations in the nebulin gene (NEB)." (PMID 35980353, 2022). "Variants in the TPM3 gene encoding γ-tropomyosin expressed in type 1 slow muscle fibers have been mostly reported with three other types of muscle disease: cap myopathy, congenital myopathy with fiber type disproportion, and nemaline myopathy." (PMID 33652732, 2021). "Mutations of tropomyosin 3 (TPM3) cause CM with nemaline myopathy, cap myopathy, and CFTD." (PMID 33435938, 2021). "Similarly, several missense mutations in TPM2 and TPM3 have been implicated in nemaline myopathy that suggest the functional importance of these genes or particular isoform in cellular function." (PMID 27703814, 2016). "Other causative genes in CRM have been reported (CFL2, ACTA1, and TPM3), although some of them are typically associated with nemaline myopathy, where cores are not present." (PMID 35980353, 2022).
nemaline myopathy (continued). "Mutations in TPM2 and TPM3 encoding for β-tropomyosin (βTm) and slow α-tropomyosin (αTm-slow) are rare cause of CMs and have been associated with a number of different entities, mainly CFTD, nemaline myopathy and cap myopathy." (PMID 32456280, 2020). "A similar finding was reported for the Met9Arg TPM3 nemaline myopathy transgenic mouse." (PMID 22174871, 2011).
congenital myopathy (17 papers, 2011 to 2025). "Recessive variants in TPM3 are rare and have hitherto mainly been seen in severe forms of NM or related congenital myopathies." (PMID 37393515, 2023). "TPM3-related myopathy (OMIM #191030) is a subtype of congenital myopathy caused by mutations in the TPM3 gene." (PMID 37936227, 2023). "Mutations of TPM2 and TPM3 (tropomyosin 3) have been reported to cause various congenital myopathies, such as CAP myopathy, Nemaline myopathy types 1 and 4, and congenital myopathies with fiber-type disproportion." (PMID 34768447, 2021). "This includes mutations in genes encoding β-TM and γ-TM isoforms (TPM2 and TPM3) in association with congenital myopathies with a range of clinical and morphological phenotypes." (PMID 23273262, 2012). "In humans, mutations in the TPM2 and TPM3 genes have been associated with congenital myopathies." (PMID 37936227, 2023). "Additionally, mutations in the TPM3 gene have been associated with the features of congenital myopathies." (PMID 37936227, 2023). "Furthermore, LCAR ameliorates congenital myopathy in a tropomyosin 3 de novo mutation transgenic zebrafish." (PMID 38136143, 2023). "We also noted a similarity in the pattern of muscle involvement between RYR1‐related congenital myopathy and the TPM3‐NM group presented here." (PMID 37265148, 2023). "The congenital myopathy substitutions R91C and R91P were in the f position of the heptad repeat, which exposed them on the outer face of the Tpm3.1265–155 coiled coil." (PMID 34834072, 2021). "Notably, three muscle-specific genes, ACTA1, TPM3, and CLCN1, were associated with hereditary skeletal myopathy and congenital myopathy." (PMID 41297061, 2025). "Comparison of involvement patterns with literature datasets highlighted preferential adductor and gracilis sparing in our ACTA1‐NM cohort, consistent tibialis posterior involvement in our TPM3‐NM cohort and a distinct MRI pattern from those derived from other NM genotypes and congenital myopathies." (PMID 37265148, 2023). "A study of the Met9Arg TPM3 transgenic congenital myopathy mouse revealed that disuse-induced muscle weakness and nemaline body formation could be mitigated with exercise." (PMID 22174871, 2011).
breast carcinoma (13 papers, 2016 to 2026). "One patient with PTC and other two malignancies (sigmoid colon cancer diagnosed before TC and breast cancer diagnosed after TC), harboring TPM3/NTRK1 and TERT C228T mutations in PTC, underwent chemotherapy treatment and subsequently died." (PMID 33923728, 2021). "Tropomyosin 3 (TPM3) mRNA, which has been associated with metastasis in breast cancer, significantly increases the platelet of breast cancer patients, which transmit TPM3 mRNA to breast cancer through PEVs, giving breast cancer a migrative phenotype." (PMID 37374185, 2023). "TPM3 is significantly upregulated in breast cancer, including in TNBC, where elevated levels correlate with poor overall survival." (PMID 41832172, 2026). "In another study, the expression of TPM3 mRNA was significantly elevated in platelets from breast cancer patients compared with age-matched healthy controls." (PMID 37686101, 2023). "In the present work, we found that when stratifying the population of cancer patients by molecular subtypes, TPM3 showed variations in mRNA levels in luminal A breast cancer in both types of samples and only in platelets of TNBC." (PMID 37176055, 2023). "The set of selected genes was composed of a group of angiogenesis-related genes (VEGF, PDGF, ANG-1, and PF-4) and genes that have been previously associated with carcinogenic or metastatic processes in breast cancer (WASF3, LAPTM4B, TPM3, and TAC1)." (PMID 37176055, 2023). "In recent years, TPM3 has been reported in many tumor diseases, including esophageal cancer, breast cancer and pancreatic cancer, but rarely reported in glioma." (PMID 37305396, 2021). "The platelet‐derived TPM3 mRNA has been shown to be delivered into the tumor through microvesicles and potentiate the migrative phenotype of breast cancer cells." (PMID 33219615, 2021). "For example, platelet TPM3 mRNA is transferred to cancer cells through microcapsules and facilitates the migration of breast cancer cells." (PMID 37305396, 2021). "Upregulation of TPM3 mRNA in platelets significantly correlated with metastasis in patients with breast cancer." (PMID 33219615, 2021). "Similarly, TIMP1 has been proposed as a biomarker in colorectal cancer (AUC 0.95) and tropomyosin 3 (TPM3) in breast cancer (AUC 0.97)." (PMID 39934930, 2025). "Interestingly, another study also reported that platelet TPM3 mRNA was delivered to breast cancer cells via microvesicles and resulted in an enhanced migratory phenotype of breast cancer cells." (PMID 37686101, 2023).
colorectal cancer (11 papers, 2019 to 2025). A primary or metastatic malignant neoplasm that affects the colon or rectum. "TPM3 fusions, although infrequent, have been identified in a wide array of malignancies including colorectal cancer, non‐small cell lung cancer (NSCLC), inflammatory myofibroblastic tumors (IMTs), and thyroid carcinomas." (PMID 41275415, 2025). "PROTAC 75 and PROTAC 76 were capable of inducing the tropomyosin 3 (TPM3)-TRKA fusion protein degradation in KM12 colorectal carcinoma cells and inhibiting downstream PLCγ1 signalling at sub-nanomolar concentrations." (PMID 35702041, 2022). "Previous studies have identified that there is a chimeric oncogene involving the tropomyosin 3 (TPM3) gene and a specific genomic locus of NTRK1 in colorectal cancer (CRC) patients." (PMID 39590120, 2024). "The rearrangement between tropomyosin 3 (TPM3) and NTRK1 in colorectal cancer was the first detected NTRK fusion." (PMID 38144536, 2023). "Of the 17 NTRK+ colorectal cancer identified, 14 cases had NTRK1‐rearranged events with TPM3 being the most frequent fusion partner, and the remaining three cases were NTRK3+ fusion cases." (PMID 35506567, 2022). "The first identified NTRK fusion was tropomyosin 3 (TPM3)-NTRK1, which was found in patients with colorectal cancer." (PMID 34209967, 2021).
colon carcinoma (9 papers, 2014 to 2023). "In KM12 colon cancer cells, the two compounds led to a decrease in tropomyosin 3 (TPM3)-TRKA fusion protein levels as well as a decrease in AGBL carboxypeptidase 4 (AGBL4)-TRKB and ETS variant TF 6 (ETV6)-TRKC fusion protein levels." (PMID 38213543, 2023). "Studies on glioma, colon cancer, and liver cancer have shown that TPM3 affects tumor occurrence and development through gene fusion and epithelial-mesenchymal transition (EMT), and has high expression levels." (PMID 37449209, 2023). "The expression levels of TPM3 are higher in stage III esophageal squamous cell carcinoma tissue compared with stage I, and glucose glycated TPM3 suppresses colon cancer cell Caco-2 proliferation." (PMID 34076143, 2021). "We then further investigated NTRK1 fusions because NTRK1, which encodes for membrane-bound TrkA protein, has been shown to be rearranged with TPM3 in colon carcinoma and papillary thyroid carcinoma." (PMID 26716414, 2016). "In particular, NTRK1 has been found to fuse with tropomyosin in colon cancer, TPM3, TPR, and TFG in thyroid cancer, and MPRIP and CD74 in lung cancer." (PMID 24647444, 2014). "The first NTRK1 gene fusion was identified in a colon cancer specimen, which had sequences from the TPM3 (non-muscle tropomyosin) gene." (PMID 26472021, 2015). "KM12 represents a human colon cancer cell line expressing TrkA and more specifically tropomyosin 3-TrkA (TPM3-NTRK1) fusion protein, since non-radiolabeled TRACK and entrectinib resulted in similar IC50 values in the nanomolar range when competing with [18F]TRACK binding in KM12 cells." (PMID 35907096, 2022).
glioma (8 papers, 2019 to 2025). A benign or malignant brain and spinal cord tumor that arises from glial cells (astrocytes, oligodendrocytes, ependymal cells). "With regard to the histological types of glioma, high expressions of TPM3 and TPM4 were evidently associated with poorer prognosis in astrocytoma and oligodendroglioma." (PMID 35892971, 2022). "Previous analyses indicated that TPM3 is the most representative oncogene for the TPM family in glioma." (PMID 35892971, 2022). "Next, the growth curves of glioma showed that U87 cells and U251 cells grew faster when TPM3 was overexpressed." (PMID 35892971, 2022). "We subsequently explored TPM3 expression in glioma cells relative to that in NHAs and discovered that TPM3 expression was elevated in the glioma cell lines measured by qRT–PCR and Western-blot assay." (PMID 37305396, 2021). "Downregulation of miR-29b-2-5p rescued the TPM3 downregulation caused by knockdown of WEE2-AS1 and the suppression of cell proliferation, migration and invasion in glioma." (PMID 37305396, 2021). "qRT-PCR identified TPM3 downregulation in sh-WEE2-AS1 transfected glioma cell lines, and miR-29b-2-5p inhibitor reversed this impact." (PMID 37305396, 2021). "A similar result was obtained from the Transwell assay: cotransfection of TPM3 and miR-29b-2-5p mimics attenuated the inhibitory effect of miR-29b-2-5p mimic treatment on the migration and invasion of glioma cell lines after miR-29b-2-5p mimic treatment." (PMID 37305396, 2021). "From these findings, we deduced that TPM3 promoted the proliferative, migratory, and invasive functions of glioma cells via the WEE2-AS1/miR-29b-2-5p axis." (PMID 37305396, 2021). "Similarly, TPM3 and TPM4 expression levels are also up-regulated in gliomas and are closely associated with poor prognosis." (PMID 37686101, 2023). "Among them, TPM3 can be used as a new independent prognostic factor for glioma." (PMID 37686101, 2023). "Moreover, further experimental investigations verified that TPM3 overexpression enhanced the proliferation and tumorigenicity of glioma." (PMID 35892971, 2022). "TPM3 overexpression enhanced the proliferation and tumorigenicity of glioma cells." (PMID 35892971, 2022). "Therefore, to ensure the correlation between TPM3 and several representative hallmarks of glioma, TPM3 was overexpressed in U87-MG and U251 cells using lentivirus, and Western blot was conducted to confirm the TPM3 overexpression." (PMID 35892971, 2022). "Through a systematic analysis of the TPM family based on the expression profile in the TCGA dataset, they identified that TPM3 might play an oncogenic role and contribute as a novel biomarker for poor prognosis in gliomas." (PMID 36138856, 2022). "The results indicated that TPMs, especially TPM3 and TPM4, may function as oncogenes, and a high expression of TPM3/4 could be correlated to a worse prognosis outcome in glioma." (PMID 35892971, 2022). "Taken together, our preliminary findings revealed that a high expression of TPM3 and TPM4 was strongly and positively correlated with poorer prognosis in glioma, and TPM3 could serve as a novel independent prognostic factor in glioma." (PMID 35892971, 2022). "High expression of TPM3 and TPM4 were positively correlated with poorer prognosis in glioma, and TPM3 could serve as a novel independent prognostic factor of glioma." (PMID 35892971, 2022). "Moreover, our subsequent bioinformatics analysis showed a candidate WEE2-AS1/miR-29b-2-5p/TPM3 axis in glioma." (PMID 37305396, 2021). "Furthermore, clinical specimens were subjected to qRT–PCR to validate TPM3 expression levels in glioma tissues vs. normal brain tissues." (PMID 37305396, 2021). "Additionally, we explored the potential molecular mechanism by which WEE2-AS1 acts as an oncogene in glioma by regulating miR-29b-2-5p/TPM3." (PMID 37305396, 2021).